STIM1 (stromal interaction molecule 1)
Diseases named in the same sentence as STIM1 in open-access papers (continued):
Sharing a sentence is not in itself a finding about the gene and the disease.
osteosarcoma (continued). "Our findings suggest that targeting Stim1 may be a potential strategy to improve the efficacy of chemotherapy for osteosarcoma." (PMID 28326487, 2017). "Stim1 represents as a target of cisplatin and blockade of Stim1-mediated Ca2+ entry may be a useful strategy to improve the efficacy of cisplatin to treat osteosarcoma." (PMID 28326487, 2017). "Here, to the best of our knowledge, our findings were the first to demonstrate that Stim1 expression could be up-regulated in chemo-resistant osteosarcoma tissues." (PMID 28326487, 2017). "Therefore, in the present study, we explored the correlation between Stim1 and ER stress under cisplatin treatment in osteosarcoma cells, demonstrating that increased Stim1 as well as Ca2+ entry contributes to cisplatin resistance by inhibition of ER stress-mediated apoptosis." (PMID 28326487, 2017). "Taken together, these results demonstrate that Stim1 as well as Ca2+ entry contributes cisplatin resistance via inhibition of ER stress-mediated apoptosis, and provide important clues to the mechanisms involved in cisplatin resistance for osteosarcoma treatment." (PMID 28326487, 2017). "Moreover, we found that cisplatin decreased Stim1 expression and SOCE in MG63 cells, but not in their resistant variants, further suggesting that increased Stim1 expression and subsequent SOCE may be a determinant of cisplatin resistance in osteosarcoma cells." (PMID 28326487, 2017). "However, the possible role of Stim1 in osteosarcoma is still inconclusive." (PMID 28326487, 2017). "Importantly, patients with Stim1-positive expression showed poorer survival than Stim1-negative patients, implying existence of Stim1 expression predicted worst survival and may as a critical prognostic indicator for osteosarcoma survival." (PMID 28326487, 2017). "Blockade of Stim1 and SOCE promoted ER-stress-mediated apoptosis induced by cisplatin, which conferred cisplatin resistance in human osteosarcoma cells." (PMID 28326487, 2017). "Targeting STIM1 or SOCE may sensitize prostate and human osteosarcoma cells to cisplatin treatment and hepatocarcinoma to 5-fluorouracil treatment by increasing autophagy, and overexpression of STIM1 increased chemoresistance in cisplatin-resistant cells." (PMID 30544747, 2018). "Interestingly, endogenous phospho-STIM1 has a high level of co-localization with endogenous cortactin, as we observed not just in C2C12 myoblasts, but also in the osteosarcoma cell line U2OS and in HeLa cells." (PMID 28341841, 2017). "In addition, we demonstrated for the first time that cisplatin decreased Stim1 expression and SOCE in cisplatin-sensitive osteosarcoma cells, but not in cisplatin-resistant cells." (PMID 28326487, 2017).
Thrombocytopenia (10 papers, 2020 to 2025). A reduction in the number of circulating thrombocytes. "In contrast to these antithrombotic effects of STIM1, the decreased vessel occlusion observed in mice bearing an EF hand mutation in STIM1 (STIM1Sax/+) is most likely triggered by the thrombocytopenia present in these mice." (PMID 35203269, 2022). "SOCE deficiency in drosophila resulting from Stim or Orai downregulation impairs the flight capacities, and zebrafish embryos injected with mRNA containing STIM1 or ORAI1 GoF mutations display thrombocytopenia, highlighting the conservation of SOCE in specific tissues." (PMID 33250786, 2020). "Mice harboring the Stim1 GoF mutations D84G, I115F, or R304W show a varying degree of multi-systemic disease signs including small size, eye movement defects, skin and spleen anomalies, bleeding diathesis with thrombocytopenia, and muscle weakness." (PMID 33250786, 2020). "Because of the key physiological role of STIM1, several point mutations associated with STIM1 gain-of-function lead to multi-systemic disorders with overlapping features, including platelet dysfunction and thrombocytopenia, bleeding diathesis, or congenital myopathy." (PMID 37759684, 2023). "In TAM/STRMK patients and murine STIM1 models, thrombocytopenia is concomitant with prolonged bleeding times, and accordingly, Orai1V109M/+ mice displayed a reduction in circulating platelets." (PMID 39594579, 2024). "The murine TAM/STRMK models similarly recapitulate the coagulation defects seen in the patients, as thrombocytopenia is evident in all three STIM1 D84G, I115F, and R304W models." (PMID 33250786, 2020). "Our patient with a STIM1 mutation had mild thrombocytopenia with large platelets but he had no Howell–Jolly bodies in his blood smear." (PMID 41300788, 2025). "However, since thrombocytopenia and anemia are observed in some TAM patients caused by STIM1 mutations, as well as three different STIM1 TAM mouse models, we conducted blood cell analyses and assessed clotting function in 8 M old WT and GS mice." (PMID 39420094, 2024). "Additional multi-systemic manifestations, including thrombocytopenia and hyposplenism, are observed in some individuals with TAM (typically in individuals with mutations in STIM1, but not ORAI1), which reflects in a clinical continuum with Stormorken and York Platelet Syndrome." (PMID 39420094, 2024).
Alzheimer disease (9 papers, 2014 to 2024). A progressive, neurodegenerative disease characterized by loss of function and death of nerve cells in several areas of the brain leading to loss of cognitive function such as memory and language. "Conversely, the decline in total STIM1 levels in brain tissue of Alzheimer’s disease patients correlates with the Braak stage, again suggesting a role for STIM1 in cell survival." (PMID 32916960, 2020). "In this report, we investigated expression levels of STIM1 in brain tissues (medium frontal gyrus) of pathologically confirmed Alzheimer’s disease patients, and observed that STIM1 protein expression level decreased with the progression of neurodegeneration." (PMID 30088035, 2018). "In the familial form of Alzheimer’s disease, SOCE was found to be attenuated and endogenous presenilin 1 interacted with STIM1 in the ER." (PMID 35821821, 2022). "In this regard, we recently reported that there is a significant reduction of STIM1 levels in human brain tissues (medium frontal gyrus) from patients diagnosed with sporadic (non-familial) Alzheimer’s disease (SAD)." (PMID 32916960, 2020). "In the brain there are two species of STIM, STIM1, which has been shown recently to link to mGluRs and play a critical role in cerebellar neurons, and STIM2 which appears to regulate influx of calcium in forebrain neurons, and be related to Alzheimer’s disease (AD) (below)." (PMID 25071469, 2014).
ectodermal dysplasia (9 papers, 2016 to 2025). "Mutations within the STIM1 gene precipitate either a complete loss or diminished protein levels, resulting in CID concomitant with ectodermal dysplasia and non-progressive muscular hypotonia." (PMID 38578569, 2024).
pancreatic cancer (9 papers, 2016 to 2024). "In pancreatic cancer, STIM1 expression was significantly linked with short survival." (PMID 38532463, 2024). "STIM1 overexpression was shown to be significantly higher in pancreatic tumor cell lines than in normal cell lines." (PMID 38532463, 2024). "Apoptosis of pancreatic cancer cells induced by chemotherapeutic agents such as 5-fluorouracil (5-FU) and gemcitabine can be enhanced by blocking STIM1 and Orai1." (PMID 37932320, 2023). "When shRNA was used to knock out hypoxia-inducible factor-1α in pancreatic cancer cells, STIM1 mRNA and protein were significantly reduced in the pancreatic cancer cells with HIF-1α gene knockout." (PMID 36187789, 2022). "Substantial evidence shows that the expression of hypoxia-inducible factor-1α in pancreatic cancer tissue is positively correlated with the expression of STIM1." (PMID 36187789, 2022). "One such example is that of the co-amplification of STIM1 in pancreatic cancer cells upon the acquisition of gemcitabine resistance, which elicits a shift in calcium signaling and transcription factor dependencies." (PMID 33919156, 2021). "HIF-1α bound to the HRE of STIM1 and elevated its expression, thereby increasing the proliferation of pancreatic cancer cells." (PMID 32587480, 2020). "For instance, in pancreatic cancer, STIM1 and Orai1 exert an inhibitory effect on apoptosis." (PMID 37932320, 2023). "HIF-1 frequently upregulates the expression of STIM1 in pancreatic cancer cells." (PMID 36187789, 2022). "Taken together, SOCE inhibition may pose an alternative treatment option for pancreatic cancer patients presenting increased STIM1 expression and a priori or acquired gemcitabine resistance." (PMID 33919156, 2021). "Assuming CM4620 and/or other SOCE inhibitors are approved by the FDA and little to mild side effects are detected, SOCE inhibitors may be suitable candidates to treat pancreatic tumors in which STIM1 is overexpressed." (PMID 33919156, 2021). "While genetic amplifications, such as the overexpression of STIM1, may protect pancreatic cancer cells from the pro-apoptotic branch of the ER stress response, they may potentially also impede them from hijacking the pro-survival branch upon hypoxia and other ER stresses." (PMID 33919156, 2021). "The study indicated STIM1 expression was upregulated, accompanied by HIF-1α overexpression in pancreatic cancer tissues." (PMID 32587480, 2020). "In pancreatic cancer, ORAI3 and STIM1 (key components of store operated calcium entry—SOCE) have been shown to be required for TGF-β-dependent SNAIL transcription and TGF-β signaling has already been associated with stroma-mediated drug resistance." (PMID 32629766, 2020). "Therefore, blocking STIM1 and ORAI1 has been shown to enhance apoptosis in pancreatic cancer cells induced by chemotherapeutic agents like 5-fluorouracil (5-FU) and gemcitabine." (PMID 39682132, 2024). "Similarly, other genes amplified upon gemcitabine resistance in pancreatic cancer are RRM1 and STIM1." (PMID 33919156, 2021).
combined immunodeficiency (8 papers, 2020 to 2025). A broad classification of inherited disorders presenting at birth that affect both the cell-mediated and humoral aspects of the immune response. "For instance, mutations disrupting Mg2+ (MAGT1) or Ca2+ (STIM1, ORAI1) transport in lymphoid cells cause combined immunodeficiencies (CID) predominantly due to defects in functions of T cells and NK cells, rather than B cells." (PMID 37273190, 2023). "The importance of calcium (Ca2+) as a second messenger in T cell signaling is exemplified by genetic deficiencies of STIM1 and ORAI1, which abolish store-operated Ca2+ entry (SOCE) resulting in combined immunodeficiency (CID)." (PMID 39560673, 2025). "Loss‐of‐function (LOF) mutations in ORAI1 or STIM1 genes (OMIM 610277 and 605921) abolish SOCE and cause CRAC channelopathy, which is characterized by combined immunodeficiency (CID), humoral autoimmunity, and ectodermal dysplasia." (PMID 32609955, 2020).
non-small cell lung carcinoma (8 papers, 2016 to 2023). A group of at least three distinct histological types of lung cancer, including non-small cell squamous cell carcinoma, adenocarcinoma, and large cell carcinoma. "TRPC1 in conjunction with STIM1 has been recently shown to induce cisplatin cytotoxicity in non-small cell lung cancer cells via reactive oxygen species and DNA damage response." (PMID 34572262, 2021). "Silencing of STIM1 or SOCE promoted apoptosis induced by cisplatin in non-small cell lung cancer cells." (PMID 30544747, 2018). "For example, Stim1 down-regulation was found to promote apoptosis induced by cisplatin in non-small cell lung cancer cells." (PMID 28326487, 2017). "Our results demonstrated that suppression of STIM1 reduced the tumor growth and formation of human non-small cell lung cancer cell line of A549 in in vitro experiments and in in vivo experiments, which confirmed our above observations that STIM1 might play an important role in lung tumorigenesis." (PMID 27863410, 2016). "One published paper reported that higher levels of STIM1 protein expression were observed in the samples of patients with non-small cell lung cancer (NSCLC) compared with adjacent non-neoplastic lung samples as detected by immunoblotting analysis and immunohistochemistry." (PMID 27863410, 2016).
atherosclerosis (7 papers, 2015 to 2024). A disease characterized by the build-up of fatty material and calcium deposition in the arterial wall resulting in partial or complete occlusion of the arterial lumen. "According to many studies, high-fat diets increase SOCE and STIM1 expression in coronary smooth cells, which is associated with enhanced atherosclerosis lesions." (PMID 37259313, 2023). "Dysregulated STIM1 function or abnormal SOCE is strongly associated with autoimmune disorders, atherosclerosis, and various forms of cancers." (PMID 39062821, 2024). "In conclusion, these studies propose that STIM1 and Orai1 are involved in atherosclerosis plaque development." (PMID 37259313, 2023). "Throughout the process, both STING (dissociated from STIMI1) and STIM1 promote atherosclerosis development." (PMID 36465175, 2022). "Thus, the mechanisms by which chronic inflammation or hyperglycaemia lead to atherosclerosis involve an increase in endothelial permeability and proliferation that depend on STIM1 and Orai1." (PMID 36834672, 2023). "The cell proliferation and migration promoted by STIM1 are also involved in atherosclerosis." (PMID 34445487, 2021). "STIM1 may thus represent a possible new therapeutic target against atherosclerosis." (PMID 25884983, 2015). "STIM1 and Orai1 also play a role in atherosclerosis, with studies showing that an increased presence SOCE in VSMCs prior to development of atherosclerosis plaques." (PMID 37259313, 2023). "During the activation of cGAS-STING, dissociated STIM1 from STING promotes atherogenesis and the development of atherosclerosis." (PMID 36465175, 2022). "Silencing STIM1 inhibits ox-LDL-induced cell proliferation and migration and hence suppresses atherosclerosis." (PMID 34445487, 2021). "Both in vitro and in vivo studies have found that STIM1 knockout reduced the increase of Ca2+ concentration in ox-LDL-induced macrophages, while genetic invalidation or pharmacological inhibition of STIM1/Orai1-mediated Ca2+ pathway attenuated the progression of atherosclerosis." (PMID 36465175, 2022).
breast tumor (7 papers, 2009 to 2019). "A reduction in ORAI1 or STIM1, both of which are essential for store-operated calcium entry, in breast tumour cells decreased tumour metastasis." (PMID 27347718, 2016). "Whether this involves store-operated Ca2+ entry requires further investigation; however, it also is noteworthy that Orai1 and STIM1 are critical for breast tumor cell migration and metastasis." (PMID 19778436, 2009).
psoriasis (7 papers, 2018 to 2025). An autoimmune condition characterized by red, well-delineated plaques with silvery scales that are usually on the extensor surfaces and scalp. "Depletion of STIM1 in neutrophils impedes their ability to infiltrate IMQ-induced psoriatic skin lesions, and STIM1 knockout mice exhibit a more rapid recovery from the psoriasis-like lesions induced by IMQ than their wild-type counterparts." (PMID 38474002, 2024). "Results and discussion: Store operated calcium (Ca2+) entry (SOCE), mediated by STIM1 and Orai1, is crucial for the function of keratinocytes and immune cells, the two major players in psoriasis." (PMID 36817139, 2023). "In a mouse model of psoriasis, targeted knockout of STIM1 in myeloid lineage cells (including neutrophils) hastened the reversal of psoriatic plaques following the removal of a chemical activator of psoriasis." (PMID 34489697, 2021). "Moreover, myeloid Stim1 deletion was not able to decrease chemokine/cytokine expression in an imiquimod-induced mouse psoriasis model, underlining that STIM1 was not essential for cytokine expression." (PMID 34201758, 2021). "In addition, calcium signaling, mediated by STIM1/ORAI1, emerges as a critical regulator of immune cell function, influencing neutrophil chemotaxis and presenting a potential target for psoriasis treatment." (PMID 38474002, 2024). "In the same way, no alteration of imiquimod-induced cytokine expression was reported in mice lacking functional STIM1 in a context of psoriasis-inflamed skin." (PMID 38292491, 2023). "They reported that the transcription of the key cytokines mediating the inflammatory response (IL‐17, IL‐22, IL‐23 and CXCL‐1 and ‐2) was not altered by STIM1 ablation in their psoriasis model." (PMID 29441588, 2018).
pulmonary hypertension (7 papers, 2013 to 2022). Increased pressure within the pulmonary circulation due to lung or heart disorder. "Considering that 2-APB is not a selective STOC blocker, new drugs with a selective effects on ORAI1/STIM1 interaction are needed to evaluate the role of the STOC in OSA patients with pulmonary hypertension." (PMID 35370769, 2022). "In addition, this can stimulate Stim1-independent Ca2+ entry through Orai3, limiting, in this way, the regression of pulmonary hypertension." (PMID 35082688, 2021). "Together, these results suggested that the components of SOCCs, including Orai1, 2, 3 and STIM1, may lead to novel therapeutic targets for the treatment of chronic hypoxia-induced pulmonary hypertension." (PMID 29188077, 2017). "Previously, STIM1 knockdown reduced store-operated Ca2+ entry and decreased hypoxia-induced PASMC proliferation, suggesting that STIM1 significantly impacts hypoxic pulmonary arterial hypertension, and CaN/NFAT shows increased activity in pulmonary arterial hypertension." (PMID 35303866, 2022). "However, STIM1 was not significantly changed in idiopathic pulmonary hypertension-PASMC." (PMID 35303866, 2022).
cardiomyopathy (6 papers, 2017 to 2022). A disease of the heart muscle or myocardium proper. "We have previously reported that mice with cardiomyocyte‐restricted deletion of STIM1 (crSTIM1−/−) exhibit progressive cardiomyopathy associated with ER stress, mitochondrial dysfunction, and metabolic dysfunction." (PMID 35179826, 2022). "For example, we found increased abundance of the STIM1 protein, which has been associated with aberrant Ca2+ handling and cardiomyopathy." (PMID 34910083, 2022). "Paradoxically, it is still unknown whether loss-of-function mutations in Stim1 or Orai1 result in heart defects or cardiomyopathies in humans." (PMID 32086252, 2020). "STIM1 knockdown in cardiomyocytes causes SAN dysfunction, reduction in heart rate, arrhythmias and lethality in adult mice while STIM1 overexpression in the heart leads to aberrant calcium handling and lethal cardiomyopathy." (PMID 34368133, 2021). "For instance, it was shown that cardio-specific knock-down of STIM1 in mice results in phenotypic dilatative cardiomyopathy." (PMID 31498847, 2019). "Additionally, cardiomyopathy in STIM1-knockout mouse hearts was progressive and age-dependent, further suggesting that any signaling functions of SOCE are likely to be homeostatic rather than developmental." (PMID 32086252, 2020). "Several groups have shown that cardiomyocytes lacking or deficient in STIM1 develop a cardiomyopathy, and we have shown that loss of cardiomyocyte STIM1 is associated with the development of mitochondrial abnormalities, ER stress, and changes in cardiomyocyte glucose and lipid metabolism." (PMID 35179826, 2022).